SUPT20HL2 (SUPT20H like 2)
Synonyms: FAM48B2; FAM48B1
Tractability: PROTAC: ubiquitination databases record sites on it.
Gene: Protein-coding gene on chromosome X (24,308,210 to 24,314,069, reverse strand). Ensembl gene ENSG00000223611.
Gene Ontology:
Molecular function: transcription coregulator activity
Biological process: regulation of transcription by RNA polymerase II
Cellular component: extracellular region; SAGA complex
Homologues: Orthologues: chimpanzee SUPT20HL2 (93% identical), tropical clawed frog supt20h (44% identical), zebrafish supt20 (43% identical), rat Supt20hl2 (38% identical), mouse Gm61616 (37% identical), mouse Gm61617 (33% identical), Drosophila melanogaster Spt20 (28% identical), rat Supt20hl1 (22% identical). Paralogues in human: SUPT20HL1 (93% identical), SUPT20H (52% identical).